NPC1 (NPC intracellular cholesterol transporter 1)
Diseases named in the same sentence as NPC1 in open-access papers (continued):
Sharing a sentence is not in itself a finding about the gene and the disease.
Niemann-Pick disease type C (continued). "Furthermore, our results that CBD disrupted cholesterol trafficking through lysosomes, when in combination with U18666A, raises the question of whether CBD use might increase the risk of toxicity in patients with Niemann–Pick disease type C, which harbor mutations in NPC1, the target of U18666A." (PMID 35753663, 2022). "CNS hypomyelination is one of the pathological characteristics of Niemann–Pick Type C disease (NPC), a rare childhood-onset neurodegenerative disorder due to mutations of NPC1 (NPC intracellular cholesterol transporter 1) or NPC2." (PMID 35678678, 2022). "Niemann–Pick disease, type C1 (NPC1) protein NPC1 was first identified and characterized as a membrane protein that when mutated causes Niemann–Pick disease, type C1, a rare autosomal neurovisceral lipid storage disorder." (PMID 35215323, 2022). "Niemann-Pick disease, type C (NPC) is a childhood-onset, lethal, neurodegenerative disorder caused by autosomal recessive mutations in the genes NPC1 or NPC2 and characterized by impaired cholesterol homeostasis, a lipid essential for cellular function." (PMID 34592985, 2021). "The lysosomal storage disorders Niemann-Pick disease Type C1 (NPC1) and Type C2 (NPC2) are rare diseases caused by mutations in the NPC1 or NPC2 gene." (PMID 33445799, 2021). "For example, NPC1 (Niemann-Pick disease, type C1), a protein containing SSD, cooperates with a secreted protein NPC2 to transport cholesterol in lysosomes." (PMID 34115759, 2021). "Niemann–Pick disease type C (NPC) is an autosomal recessive, neurodegenerative disease caused by mutations in either the NPC1 or NPC2 genes." (PMID 34535129, 2021). "Since a folding defect of NPC1 plays a critical role in the etiology of Niemann-Pick disease type C, efforts have been made to identify drug candidates that can improve the folding efficiency of NPC1 mutant proteins." (PMID 33315900, 2020). "In Niemann-Pick disease, type C (NPC), excess cholesterol accumulation in the endo-lysosomal compartment is caused by defects in one of two lysosomal proteins, either NPC1 or NPC2." (PMID 31999726, 2020). "TMEM97 is the recently identified σ2 receptor that binds to the intracellular cholesterol trafficking protein NPC1 (Niemann-Pick disease, type C1), reducing its abundance and in turn cholesterol transfer to the ER." (PMID 30578317, 2019). "The accumulation of lipids in the late endosomes and lysosomes of Niemann–Pick type C disease (NPCD) cells is a consequence of the dysfunction of one protein (usually NPC1) but induces dysfunction in many proteins." (PMID 30736449, 2019). "In this review, we focus on Niemann–Pick disease type C1 (NPC1), which is a rare lipid-storage disorder." (PMID 31500175, 2019). "As a suitable example, we prepared coronal cryosections of cerebelli of NPC1 I1061T knock-in mice, an animal model of Niemann-Pick type C disease, featuring a spatially restricted neuronal lipid disorder and C57BL/6 control mice." (PMID 29321555, 2018). "Niemann-Pick disease type C (NPC; OMIM 257220) is a rare autosomal recessive, lysosomal and multisystemic neurodegenerative disorder caused by mutations in either the NPC1 or NPC2 gene." (PMID 28167839, 2017). "Niemann-Pick disease type C (NPC) is an autosomal recessive and neurodegenerative disease caused by mutations in either the NPC1 (95% of cases) or the NPC2 gene (5% of cases)." (PMID 29156730, 2017). "These were the genes encoding for Galactosidase A (GLA), Scavenger receptor class B member 2 (SCARB2), Niemann-Pick disease, type C1 (NPC1) and the CD164 molecule (CD164)." (PMID 29238336, 2017). "Niemann–Pick disease, type C1 (NPC1) is a neurodegenerative, lysosomal storage disorder due to mutation of the NPC1 gene." (PMID 26986514, 2016). "Their inherited deficiencies lead to Niemann-Pick disease type C. NPC2 can pick up cholesterol directly from inner membranes and transfer it to NPC1 or other vesicular membranes." (PMID 25339683, 2014).
Niemann-Pick disease type C (continued). "Niemann Pick disease type C (NP-C; OMIM#257220 and OMIM#607625) is a rare autosomal recessive, multisystemic, neurodegenerative condition caused by mutations in the NPC1 or the NPC2 gene." (PMID 25145893, 2014). "Previous functional studies have shown that miR33a regulates expression of genes in cellular pathways of cholesterol transport, including ABCA1 (ATP binding cassette transporter) and the lysosomal transporter protein NPC1 (Niemann-Pick disease, type C1)." (PMID 22984453, 2012). "Niemann-Pick Type C disease (NPC) is a lethal, autosomal recessive disorder caused by mutations in the NPC1 and NPC2 cholesterol transport proteins." (PMID 23144769, 2012). "Niemann Pick disease type C1 is a LSD of autosomal recessive inheritance, caused by mutations in the NPC1 gene that encodes for a large transmembrane protein." (PMID 22163015, 2011). "Reassuringly, known late endosome specific proteins such as the small GTPase Rab7, the lysosomal glycoprotein LAMP2, or the NPC1 protein involved in Niemann Pick type C disease were found." (PMID 18648502, 2008). "For example, in mouse models of Niemann-Pick type C disease, all Purkinje cells express the mutant NPC1 protein but zebrin II-immunonegative Purkinje cells are far more susceptible to its effects." (PMID 18301736, 2008). "A prime example is Niemann–Pick type C disease (NPCD), where cholesterol export from the endosomal–lysosomal system is impaired due to variants of either NPC intracellular cholesterol transporter 1 (NPC1) or NPC intracellular cholesterol transporter 2 (NPC2)." (PMID 40565243, 2025). "A polymorphism in the NPC1 or NPC2 gene is associated with lysosomal cholesterol accumulation and, consequently, with the Niemann–Pick disease type C, a human neurodegenerative lysosomal lipid storage disorder associated with the early onset of Crohn’s Disease." (PMID 40943172, 2025). "For example, loss of NPC1 in Niemann Pick Disease type C leads to accumulation not only of cholesterol, but also secondary perturbations in sphingolipids and glycosaminoglycans." (PMID 37200393, 2023). "We used a mouse model of the NPC1-associated form of NPC (NPC1; Niemann–Pick disease type C1), that is, characterized by a non-detectable expression of the NPC1 protein and has been widely used as an acutely progressive neurodegenerative model of the disease." (PMID 37369603, 2023). "For example, in NPC1 and NPC2, which cause Niemann-Pick disease type C, no NPC1 variants were identified in the WGS data from the 1495 individuals in the TWB, and only one NPC2 variant was identified." (PMID 37741878, 2023). "Niemann-Pick disease type C (NPC) is characterized by genetic anomalies in the NPC1 and NPC2 genes." (PMID 38098077, 2023). "We suspect that the larger LAMP1 species (120 kDa) may be caused by hyper-glycosylation, as previously observed in in brain of Niemann-Pick disease type C1 (NPC1) from mouse models and patients." (PMID 36113749, 2022). "Niemann–Pick type C disease (NPCD-MIM 257220; MIM607625) is an autosomal recessive neurovisceral lysosomal storage disorder due to mutations in the NPC1 (95% of patients) or NPC2 genes, encoding two proteins involved in the intracellular trafficking of cholesterol and other lipids." (PMID 34682919, 2021). "A single-amino-acid mutation of the sterol-sensing domain of NPC1, namely, NPC1P692S, results in decreased LDL-derived cholesterol delivery to endoplasmic reticulum and the plasma membrane, similar to what is observed in Niemann-Pick type C disease." (PMID 34544283, 2021). "Niemann–Pick type C disease (NPC-MIM 257220; MIM607625) is an autosomal recessive lysosomal storage disorder due to mutations in NPC1 (95% of patients) or NPC2 genes, encoding two proteins involved in the intracellular trafficking of cholesterol and other lipids." (PMID 32138288, 2020).
Niemann-Pick disease type C (continued). "Niemann-Pick disease, type C1 (NPC1) is a rare, autosomal recessive, lipid storage disorder caused by mutations in NPC1, thereby resulting in intracellular lipid trafficking defects leading to the accumulation of unesterified cholesterol and sphingolipids in the late endosomal/lysosomal system." (PMID 30870990, 2019). "Moreover, BALB/cJ Npc1nih mice with NPC1 haploinsufficiency, an animal model of type C Niemann-Pick disease, are characterized by increased anxiety-like behavior in early maturity." (PMID 31333574, 2019). "Hypomyelination in the central nerves system (CNS) is one of the most obviously pathological features in Niemann-Pick Type C disease (NPC), which is a rare neurodegenerative disorder caused by mutations in the NPC intracellular cholesterol transporter 1 or 2 (Npc1 or Npc2)." (PMID 30866987, 2019). "Niemann-Pick disease type C (NPC) is a neurodegenerative and lysosomal lipid storage disorder, characterized by the abnormal accumulation of unesterified cholesterol and glycolipids, which is caused by mutations in the NPC1 genes." (PMID 29156730, 2017). "The genes contributing to these GO pathways in the DILGOM sample were ATP-binding cassette, sub-family G, member 1 (ABCG1), caveolin 1 (CAV1), Niemann-Pick disease, type C1 (NPC1), and Niemann-Pick disease, type C1, gene-like 1 (NPC1L1), while in the experimental SR study they were ABCA1 and NPC1." (PMID 27102866, 2016). "Increasing endolysosomal cholesterol levels in Niemann-Pick disease type C, caused by an inherited defect of a steroid transfer protein, either NPC2 or NPC1, are accompanied by an accumulation of SM, glycosphingolipids, sphingosine, and the anionic endolysosomal marker phospholipid, BMP." (PMID 25339683, 2014). "Although in non-HD models, lithium downregulated REST binding and protein levels in a rat fetal alcohol syndrome model whereas valproate upregulated REST transcription in medulloblastoma cells but neuroprotectively repressed REST in the Niemann-Pick Type C disease NPC1 knockout mouse." (PMID 24248060, 2013). "In non-HD models, lithium downregulated REST binding and protein levels in a rat fetal alcohol syndrome model whereas valproate upregulated REST transcription in medulloblastoma cells, but neuroprotectively repressed REST in the Niemann-Pick Type C disease NPC1 knockout mouse." (PMID 24248060, 2013). "Mutations in the gene are responsible for a rare and fatal lipid storage disorder, Niemann-Pick disease type C. The product of NPC1 resides in the limiting membrane of late endosomes and lysosomes where it facilitates lipid transport to various cellular compartments." (PMID 23153210, 2012). "Here, NPC1 null cells (CHO-NPC1−/−), exhibiting increased cholesterol levels and disturbed cholesterol transport similar to that observed in Niemann-Pick type C disease (NPC), were used to analyze the influence of altered cholesterol levels on APP-BACE1 proximity." (PMID 23443094, 2012). "Niemann-Pick disease, type C1 (NPC1, MIM 257220) is an autosomal recessive, inborn error of intracellular cholesterol transport due to impaired function of NPC1." (PMID 38673803, 2024). "Niemann-Pick disease type C (NPC) is a genetic, rare, highly heterogeneous, and progressive lysosomal disorder characterized by the dysfunction of NPC1 or NPC2 proteins, which leads to the accumulation of multiple lipid species." (PMID 39061081, 2024). "In the Niemann-Pick disease Type-C (NPC), the impaired transport of cholesterol from the ER to the plasma membrane by defects in the Npc1 gene, induces an accumulation of intracellular cholesterol, endosomal alterations, and cell death." (PMID 37900943, 2023). "Meanwhile, mutations in NPC Intracellular Cholesterol Transporter 1 or 2 (NPC1 or NPC2) alter cellular cholesterol trafficking and lipid metabolism disruption, leading to Niemann-Pick’s disease type C1 and C2." (PMID 34202192, 2021).
Niemann-Pick disease type C (continued). "Recently, Niemann–Pick disease type C (NPC), a lysosomal storage disorder in which the NPC1 gene coding for a lysosomal protein involved in lipid transport is mutated, was also linked to early onset Crohn’s disease." (PMID 29743550, 2018). "Interestingly, the sequence polymorphism at NPC1 residue 502 did not impair cholesterol clearance from lysosomes, and none of the residues under positive selection were found to be mutated in Niemann-Pick type C disease patients." (PMID 26698106, 2015). "The Filipin test was normal and NPC1 gene sequencing was negative, which excluded a diagnosis of Niemann Pick type-C disease." (PMID 33804237, 2021). "Niemann-Pick type C disease (NPC) is a rare inherited neurodegenerative disorder characterized by an accumulation of intracellular cholesterol within late endosomes and lysosomes due to NPC1 or NPC2 dysfunction." (PMID 34948052, 2021). "In addition, our genetic mutation rates in EOPSP are based on pathogenic mutations that are directly genotyped on the Illumina NeuroChip, and targeted NPC1 and NPC2 sequencing was limited to cases that had biochemical evidence of Niemann‐Pick type C disease." (PMID 31299107, 2019). "This is correlated with a reduction or absence of detectable NPC1 (Niemann–Pick disease, type C1), a protein responsible for cholesterol efflux from endocytic compartments, in the Leishmania mexicana habitat and infected cells." (PMID 28349644, 2017). "The patient did not have a pattern of clinical deterioration to suggest Niemann-Pick Disease type C (NPC1 [MIM 257220] and NPC2 [607625]) but, given the gaze palsy, defects in NPC1 and NPC2 were excluded through single gene sequencing." (PMID 25885783, 2015). "Mice lacking Npc1 function display a phenotype recapitulating Niemann-Pick disease type C, whereas haploinsufficiency for the gene results in weight gain and insulin resistance." (PMID 23153210, 2012). "However, no in vitro model for Niemann-Pick disease Type C1 (NPC1) based on hiPS cells is currently available." (PMID 24044630, 2013). "When NPC1 or NPC2 are not produced or the produced proteins are abnormal, it leads to lipid accumulation inside the lysosomes and the development of Niemann-Pick type C disease." (PMID 34596813, 2021). "However, the relationship between NPC1 and FLOTs in uninfected or A. phagocytophilum-infected cells remains unknown, except for one study showing that the FLOT2-dependent release of cholesterol from exosomes ameliorates cellular cholesterol accumulation in Niemann-Pick type C disease." (PMID 34544283, 2021).
lysosomal storage disorder (97 papers, 2010 to 2026). "Niemann–Pick disease type C (NPC) is a lysosomal storage disease that is characterized by progressive neurological deterioration due to mutations in the genes encoding the NPC1 (95% of cases) or NPC2 (5% of cases) proteins." (PMID 39518914, 2024). "Niemann–Pick type C (NPC) disease is an autosomal recessive lysosomal storage disorder where 95% of the cases are caused by mutations in the Niemann–Pick C1 (NPC1) gene." (PMID 39518914, 2024). "Niemann–Pick type C (NPC) is a lysosomal storage disorder (LSD) caused by pathogenic variants in either the NPC1 or NPC2 genes, which encode proteins involved in the lysosomal export of unesterified cholesterol." (PMID 39596250, 2024). "Purkinje cell (PC) loss occurs at an early age in patients and animal models of Niemann-Pick Type C (NPC), a lysosomal storage disease caused by mutations in the Npc1 or Npc2 genes." (PMID 37024714, 2023). "Niemann–Pick type C (NP-C) disease is a rare lysosomal storage disease caused by mutations in NPC1 (95% cases) or NPC2 (5% cases)." (PMID 37440478, 2023). "NPC, type C1 (NPC1) is a lysosomal disorder linked to mutations in the NPC1 gene, leading to the abnormal trafficking and accumulation of lipids, primarily cholesterol, in brain cells." (PMID 37507857, 2023). "Niemann-Pick type C1 (NPC1) disease is a progressive lysosomal storage disorder caused by mutations of the NPC1 gene." (PMID 35007562, 2022). "Structural and functional alterations in NPC1 are associated with several lysosomal storage disorders." (PMID 35631123, 2022). "NPC1 disease is one of many lysosomal storage diseases and results mainly from a mutation that inactivates the NPC1 protein responsible for the transport of unesterified cholesterol from the late endosomal/lysosomal compartment to the cytosol in every cell." (PMID 36614015, 2022). "Niemann-Pick type C (NPC) disease is an autosomal recessive lysosomal storage disease that is caused by a mutation of the NPC1 or NPC2 gene, in which un-esterified cholesterol and sphingolipids accumulate mainly in the liver, spleen, and brain." (PMID 33986646, 2021). "NPC is a rare neurodegenerative lysosomal storage disorder caused by mutations in the NPC1 (95% of the cases) or NPC2 genes, which are involved in cholesterol trafficking." (PMID 33917666, 2021). "TRPML1 has been shown to be less active in lysosomal storage disorders including NPC1 deficiency and calcium signaling has been reported to be disturbed in NPC1 deficient cells." (PMID 33903617, 2021). "Mutations in Niemann–Pick type C 1 (NPC1) cause lysosomal storage disease due to defective lysosomal cholesterol export and can be chemically mimicked by U18666A." (PMID 33145969, 2021). "Dysregulation of cathepsin enzymatic activity has been proposed to be a pathogenic factor in multiple lysosomal storage diseases including NPC1." (PMID 32731618, 2020). "Niemann–Pick type C (NPC), a lysosomal storage disorder, is mainly caused by mutations in the NPC1 gene." (PMID 32244854, 2020). "The NPC1 transporter is critical for lysosomal export of LDL-derived cholesterol and cellular cholesterol homeostasis and NPC1 mutations are the primary cause of the Niemann Pick type C lysosomal storage disease." (PMID 33144569, 2020). "The disease Niemann-Pick type C1 (NPC1) is a rare neurovisceral lysosomal storage disorder that is caused by autosomal recessive mutations in the NPC1 gene." (PMID 33081384, 2020). "Niemann-Pick type C (NPC) disease is an autosomal recessive lysosomal storage disorder caused by mutations in NPC1 or NPC2 genes." (PMID 32138288, 2020). "Niemann-Pick C disease (NPC) is an autosomal recessive lysosomal storage disorder resulting from mutations in the NPC1 (95% of cases) or NPC2 genes." (PMID 30847690, 2019). "Niemann-Pick disease type C (NPC) is an autosomal recessive lysosomal storage disorder resulting from mutations in the NPC1 (95% of cases) or NPC2 genes." (PMID 30847690, 2019).